IGKV2D-29 (immunoglobulin kappa variable 2D-29)
Description:
V region of the variable domain of immunoglobulin light chains that participates in the antigen recognition. Immunoglobulins, also known as antibodies, are membrane-bound or secreted glycoproteins produced by B lymphocytes. In the recognition phase of humoral immunity, the membrane-bound immunoglobulins serve as receptors which, upon binding of a specific antigen, trigger the clonal expansion and differentiation of B lymphocytes into immunoglobulins-secreting plasma cells. Secreted immunoglobulins mediate the effector phase of humoral immunity, which results in the elimination of bound antigens. The antigen binding site is formed by the variable domain of one heavy chain, together with that of its associated light chain. Thus, each immunoglobulin has two antigen binding sites with remarkable affinity for a particular antigen. The variable domains are assembled by a process called V-(D)-J rearrangement and can then be subjected to somatic hypermutations which, after exposure to antigen and selection, allow affinity maturation for a particular antigen.
Synonyms: A2a; A2c; IGKV2D29
Gene: Immunoglobulin variable (V) gene on chromosome 2 (89,947,512 to 89,948,269, forward strand). Ensembl gene ENSG00000243264.
Subcellular location: Secreted; Cell membrane
Gene Ontology:
Biological process: immune response
Cellular component: extracellular region; immunoglobulin complex; plasma membrane
Homologues: Orthologues: mouse Igkv2-109 (78% identical). Paralogues in human: IGKV2D-40 (87% identical), IGKV2-28 (85% identical), IGKV2D-28 (85% identical), IGKV2D-26 (84% identical), IGKV2-24 (83% identical), IGKV2D-24 (82% identical), IGKV2-30 (81% identical), IGKV2D-30 (80% identical), IGKV2-40 (73% identical), IGKV4-1 (60% identical), IGKV3-20 (59% identical), IGKV3-11 (58% identical), and 81 more.
Diseases named in the same sentence as IGKV2D-29 in open-access papers:
IGKV2D-29 is named in the same sentence as 44 diseases in open-access papers, as found by Europe PMC text mining. Sharing a sentence is not in itself a finding about the gene and the disease.
IGKV2D-29 shares sentences with these, for which no sentence is quoted: tumor (13 papers); Parkinson disease (11); cancer (9); depression (4); Dyskinesia (4); Anxiety (3); ischemia (3); neurodegenerative disease (3); Alzheimer disease (2); brain ischemia (2); colitis (2); infection (2); multiple sclerosis (2); Acute hepatitis (1); acute pancreatitis (1); atherosclerosis (1); Autoimmunity (1); bipolar disorder (1); breast carcinoma (1); cardiac hypertrophy (1); Cerebral ischemia (1); clostridium difficile infection (1); cocaine dependence (1); colon adenocarcinoma (1); colon carcinoma (1); COVID-19 (1); Crohn disease (1); epilepsy (1); hepatocellular carcinoma (1); liver fibrosis (1).
A further 14 diseases each share a sentence with IGKV2D-29 in 1 paper.